NRP2 (neuropilin 2)
Diseases named in the same sentence as NRP2 in open-access papers (continued):
Sharing a sentence is not in itself a finding about the gene and the disease.
pancreatic cancer (19 papers, 2011 to 2025). "In this study, the expression of NRP2 is elevated and associated with unfavorable prognosis in pancreas carcinoma." (PMID 34336654, 2021). "Here, we detected the elevated NRP2 was associated with the poor prognosis of pancreas carcinoma." (PMID 34336654, 2021). "We could also observe an inverse correlation between NRP2 and Epcam in several pancreatic cancer cell lines, confirming that NRP2 is quite associated with a mesenchymal phenotype of cancer cells." (PMID 21747928, 2011). "Moreover, NRP2 is expressed by a vast majority of endocrines pancreatic tumors, suggesting that NRP2 can be used as a diagnostic marker for these tumors." (PMID 24212788, 2011). "In malignancies such as ovarian and pancreatic cancer, MUC16 CTD translocation drives the expression of invasion-related genes, such as NRP2 in pancreatic cancer, promoting disease progression." (PMID 40305342, 2025). "The GDMCN2 system consists of MOFs enclosed in a COF and modified with the pancreatic cancer‐specific antibody NRP2." (PMID 37661565, 2023). "To address this issue, we designed a novel drug delivery system named GDMCN2,which uses iron‐based metal organic framework (Fe‐MOF) nanocages encased in a covalent organic framework (COF) and modified with the pancreatic cancer‐specific antibody, NRP2." (PMID 37661565, 2023). "NRP2 is upregulated on macrophages following in vitro differentiation from progenitors and is present on TAMs within pancreatic cancers." (PMID 35651620, 2022). "Collectively, the level of NRP2 was significantly raised in pancreatic carcinoma tissues and had higher sensitivity and specificity to differentiate pancreatic cancer from para-carcinoma tissues." (PMID 34336654, 2021). "The ROC curve was created by sensitivity and specificity of NRP2 scores and provided the AUC (0.7887) to distinguish pancreatic cancer from normal tissues (95% CI: 0.7028 to 0.8745; P < 0.0001)." (PMID 34336654, 2021). "Although not as intensely explored for functions of NRP-2 in PDAC, it is reliable that NRP-2 is involved in biological processes of pancreatic cancer such as cell survival and invasion." (PMID 34336654, 2021). "The survival analysis showed that Overall Survival and Disease-Free Survival of pancreatic cancer patients with high NRP2 levels were significantly lower than patients with low NRP2 levels (p < 0.05)." (PMID 34336654, 2021). "The level of NRP2 was significantly up-regulated in pancreatic cancer tissues compared with normal pancreatic tissues (P< 0.05)." (PMID 34336654, 2021). "Previously, we have shown that NRP-2 is expressed on colon and pancreatic cancer cells and that its expression is involved in promoting tumor growth." (PMID 22028766, 2011). "NRP-2 expression has been reported on tumor cells in lung cancer, neuroblastoma, pancreatic cancer, osteosarcoma, and bladder cancer." (PMID 22028766, 2011). "Therefore, scRNA-seq data suggested that tumor fibrosis in pancreatic cancer was promoted via the PlGF-NRP1/NRP2 axis, which induced collagen production through secreted Inhba from the CAF-2 population." (PMID 36272973, 2022). "However, the application value of NRP2 as a therapeutic target in pancreatic cancer is still unclear." (PMID 34336654, 2021). "We assessed the role of NRP2 in pancreatic carcinoma via the GEPIA database." (PMID 34336654, 2021). "MiR-1247 was able to suppress the proliferation of pancreatic cancer cells through targeting NRP2." (PMID 32373927, 2020). "NRP2, a putative target of miR-331-3p, which is a co-receptor of semapholin 3 and vascular endothelial growth factor family members, acts as an oncogene and shows high expression in some human carcinomas including lung, colorectal, and pancreatic cancers and glioblastoma." (PMID 27548144, 2016). "In a normal pancreas, there is an absence of NRP1 and a presence of NRP2 in the endocrine islets and acinar cells, while in pancreatic cancer cells, both NRP1 and NRP2 are highly expressed." (PMID 40277760, 2025).
pancreatic cancer (continued). "MUC16 upregulates Neuropilin 2 (NRP2) through JAK2 / STAT1 signaling in PDAC and promotes metastasis of pancreatic cancer." (PMID 38758220, 2024). "As the treatment requires a direct interaction between NRP2 and N2E4, N2E4 shows more practical effects on pancreatic cancer cell lines and xenografts with high NRP2 expression." (PMID 34336654, 2021). "In this work, we comprehensively assessed the expression of NRP2 in pancreatic cancer, identified the N2E4 target protein (NRP2) in PDAC cells, and further elucidated the positive therapeutic effect of N2E4 in vitro and in vivo and the underlying mechanisms." (PMID 34336654, 2021). "Expression levels of NRP1, NRP2 and GIPC1 in nine pancreatic carcinoma cell lines were tested by RT-qPCR and revealed major differences." (PMID 31664117, 2019). "NRP2, an isoform of NRP1, was previously shown to transduce the activation of Akt in pancreatic cancer cells." (PMID 26209534, 2015). "Moreover, several growth factors and inflammatory cytokines are involved in NRP regulation too: In pancreatic cancer cells, IL-6 enhances NRP1 expression whereas IL-8 increases NRP2 expression via activation of ERK1/2 pathway." (PMID 24212788, 2011).
glioma (16 papers, 2008 to 2025). A benign or malignant brain and spinal cord tumor that arises from glial cells (astrocytes, oligodendrocytes, ependymal cells). "For example, the VEGFR2 axis was shown to promote the viability and growth of glioma stem-like cells, and NRP2 has been implicated in breast tumor initiation." (PMID 25358638, 2014). "SEMA3A (Semaphorin 3A) is known to promote the invasion and migration of glioma cells, while NRP2 (Neuropilin-2) regulates the migratory ability of glioma cells in response to SEMA3A." (PMID 36231068, 2022). "Mouse genetics and other studies have found that Plexins A1, A2, and D1 in association with Nrp1 and Nrp2 are receptors for SEMA3C in endothelial cell and glioma stem cells." (PMID 29348142, 2018). "One study supports that Nrp2 expression is low in both low- and high-grade gliomas while another study suggests that Nrp2 is expressed highly in 37% of glioblastoma and that its concomitant overexpression with VEGF-C correlates with poor patient survival." (PMID 29642487, 2018). "Even though NRP1 acts mainly as a SEMA3A receptor, and NRP2 as a SEMA3F receptor in neurons, NRP2 can compensate for NRP1 as a SEMA3A-receptor during glioma cell migration in vitro and in vomeronasal axon guidance in mouse embryos in vivo." (PMID 26923176, 2016). "In conclusion, SEMA3B, SEMA3G and NRP2 expressions were related to prolonged survival of adult patients with glial tumours." (PMID 18781179, 2008). "In this study, we analysed mRNA expression of class-3 semaphorins, in addition to SEMA4D, VEGF, NRP1 and NRP2 expressions, in 38 adult glial tumours." (PMID 18781179, 2008). "Moreover, in the study by Karyian-Tapon and co-authors, higher mRNA expression of SEMA3B, SEMA3G and NRP2 were related to prolonged survival of patients with the diagnosis of glial tumors." (PMID 33036421, 2020). "Hence, NRP1 and NRP2 were identified as candidate special receptor of GDNF in C6 glioma cells and we chose to further investigate NRP1 in this study." (PMID 29088765, 2017). "As VEGF165 binds to NRP2, competition between SEMA3B/3G and VEGF165 for binding to NRP2 might exist in gliomas as demonstrated for SEMA3A and NRP1 in ECs." (PMID 18781179, 2008). "SEMA3F also induces formation of NRP2–PLXNA1 complex, which recruits ABL2 and p190 to inactivate RhoA, inhibiting cell migration and contractility of U87 MG glioma cells." (PMID 41391772, 2025). "This is consistent with previous reports that SEMA3F forms a complex with NRP2 and PLXNA1 within 5 min upon treatment on human glioma cells and induced the reduction in phosphorylation of downstream signaling molecules between 5 and 20 min." (PMID 41391772, 2025). "GO analysis on the list of the DEPs identified by mass spectrometry using the PANTHER Classification System showed that 3 cell adhesion molecules, NRP1, NRP2 and ATRN, were putative GDNF receptors in glioma cells with roles in biological adhesion and growth." (PMID 29088765, 2017). "Statistical analysis indicated that SEMA3B, SEMA3G and NRP2 expressions were related to prolonged survival and that SEMA3D expression was reduced in high-grade as compared with low-grade gliomas." (PMID 18781179, 2008). "We studied by quantitative real-time RT–PCR the expression of the seven semaphorins from class-3 (A-G), SEMA4D, NRP1, NRP2 and VEGF in 11 adult low-grade and 27 high-grade gliomas." (PMID 18781179, 2008). "Similar to NRP2, NRP1 is expressed on various types of tumor cells and its expression correlates with tumor progression or a poorer prognosis in several cancers such as prostate, breast, non-small-cell lung carcinoma (NSCLC) and glioma." (PMID 33918816, 2021). "This does not mean that DRP2, IGFBP5, KLF10, ARHGAP11A and NRP2 are not essential genes for glioma pathogenesis, given the missing data and limited sample size we found." (PMID 34434651, 2021).
glioma (continued). "The quantitative real-time PCR method was used to evaluate mRNA expression of SEMA3(A-G), neuropilins (NRP1 and NRP2), plexins (PLXNA2 and PLXND1), cadherins (CDH1 and CDH2), integrins (ITGB1, ITGB3, ITGA5, and ITGAV), VEGFA and KDR genes in 59 II-IV grade glioma tissues." (PMID 33036421, 2020). "Several angiogenesis-related molecules such as Laminin, Neuropilin-2 and CD105 have been reported to be enriched in glioma stem cells capable of forming vascular structures in vitro, implicating that TDEC transdifferentiation is facilitated by a glioma stem-like phenotype." (PMID 26203665, 2015). "RNA interference (RNAi) to inhibit NRP-2 expression in vitro decreased the growth and clonogenic growth of GBM cell lines, providing further support for an oncogenic role for NRP-2 in high-grade gliomas." (PMID 24142150, 2014). "Two (ARHGAP11A, NRP2) of them showed no big difference between normal and glioma samples." (PMID 34434651, 2021). "However, more recently Sema3a has been found to bind to COS cells expressing Nrp2 (albeit 1.3 fold less than Nrp1 expressing COS cells), and a functional blocking antibody against Nrp2 removes the chemorepulsive effect of Sema3a on at least one human glioma cell line in vitro." (PMID 22783168, 2012). "For the other studied genes (SEMA3A, B, C, E, F, G, NRP1, NRP2 and SEMA4D), we did not observe statistical difference between low- and high-grade gliomas." (PMID 18781179, 2008).
melanoma (15 papers, 2008 to 2025). A malignant, usually aggressive tumor composed of atypical, neoplastic melanocytes. "We also detected neuropilin-2, whose expression is known to be associated with melanoma progression." (PMID 33467521, 2021). "NRP2 was recently found to be an oncogene involved in accelerating melanoma tumor growth and progression in vivo." (PMID 32983966, 2020). "Next, we validated the highest significantly down- (Myh2, Mybh, Sypl2, Xirp1, Mybpc1) and up- (Fcgbp, Areg) regulated genes, including the melanoma-specific genes (Dmnt1 and Nrp2) identified by RNA sequencing following treatment with SAM+anti-PD-1 by RT-qPCR." (PMID 32983966, 2020). "NRP2 showed significantly high expression in the primary tumors and metastatic tissues of the melanoma patient samples although normal tissues had low expression." (PMID 32983966, 2020). "Unlike NRP1, which is more likely to be expressed by carcinomas, NRP2 is rather expressed in neuronal tumors and in melanomas." (PMID 30717262, 2019). "SEMA3F overexpressing melanoma cells form poorly vascularized tumors because Nrp2 inhibits tumor development and metastasis by a strong antiangiogenic cascade." (PMID 30717262, 2019). "A mutant form of NRP2 (MutB-NRP2) that acts as a decoy and binds to VEGF with eightfold increased affinity compared with wild-type NRP2 reduced tumor burden in a xenograft model using melanoma cells, alone and when used in combination with bevacizumab." (PMID 29067024, 2017). "Immunohistochemical investigations have revealed that melanomas show high expression of neuropilin-2 and that the expression is higher in lymph node metastases than in the primary tumor." (PMID 29017512, 2017). "NRP2 is overexpressed in many cancer cell types, including astrocytoma, neuroblastoma, melanoma, and pituitary and ovarian cancers." (PMID 26673618, 2016). "The expression of NRP-2 has been detected on tumor cells of patient samples of many tumor types, including glioblastoma, neuroblastoma, and melanoma." (PMID 22028766, 2011). "Moreover, high expression of NRP2 was found to have significantly low overall survival and progression-free survival rates (p < 0.0001) in melanoma patients." (PMID 32983966, 2020). "In addition, NRP2 had the highest expression in melanoma TCGA data compared to all other cancers in the TCGA Pan-Cancer Atlas." (PMID 32983966, 2020). "Furthermore, NRP2, PLXNC1 and PLXNB3 were also positively associated with cell sensitivity to Dabrafenib, which is the treatment for late-stage melanoma and metastatic non-small cell lung cancer with BRAF V600E or V600K mutations." (PMID 32640719, 2020). "In addition, NRP2, PLXNA1, PLXNC1, and PLXNB3 were found to be all positively associated with cell sensitivity to Vemurafenib, which is used for the treatment for late-stage melanoma." (PMID 32640719, 2020). "Furthermore, combined blockade of NRP-2 action and treatment with bevacizumab anti-angiogenic therapy produced synergistic inhibition of melanoma xenograft growth, a finding that has implications for GBM treatment given the emerging therapeutic role of bevacizumab in this disease." (PMID 24142150, 2014). "We analyzed a few of the top DEGs (NRP2, CAPN3, DMBT1, BRAF, DDIT3, PPP1R3C, NF1) using The UCSC Xena platform that has large number of RNA-seq data of normal tissue from healthy individuals (GTEx) and primary tumor and metastatic tissue data from melanoma patients (TCGA)." (PMID 32983966, 2020).
colorectal cancer (14 papers, 2011 to 2025). A primary or metastatic malignant neoplasm that affects the colon or rectum. "Neuropilin-2 (Nrp2), an important regulator of lymphangiogenesis and lymphatic metastasis, has been associated with progression in colorectal cancer (CRC)." (PMID 35158941, 2022). "Indeed, the presence of neuropilin-2 in colorectal carcinoma cell lines was correlated with loss of epithelial markers such as cytokeratin-20 and E-cadherin and with acquisition of mesenchymal molecules such as vimentin." (PMID 21747928, 2011). "Numerous analyses have shown that enhanced expression of NRP-1 and NRP-2 in colorectal cancer tissues correlates with adverse patient prognosis, including a higher risk of metastasis and shorter overall survival." (PMID 40430075, 2025). "In colorectal cancer, NRP-1 overexpression is linked to greater invasiveness and reduced survival, while NRP-2 is associated with faster tumor growth." (PMID 40430075, 2025). "Many cancer types are reported to have high lymphangiogenic receptor Neuropilin-2 (Nrp2) expression, including colorectal cancer (CRC)." (PMID 35158941, 2022). "NRP-2’s connection to colorectal cancer is still under investigation, as is the method by which it is regulated." (PMID 35052853, 2022). "This systematic review aims to highlight the ability of neuropilin-2 in the epithelial-mesenchymal transition in colorectal cancer cells." (PMID 35052853, 2022). "The following search terms were used: “neuropilin-2” “neuropilin 2”, “NRP2” and “NRP-2”, “colorectal cancer”, “colon cancer”." (PMID 35052853, 2022). "When neuropilin-2 was found in colorectal cancer cell lines, researchers discovered that epithelial markers like cytokeratin-20 and E-cadherin were lost and mesenchymal molecules like vimentin were acquired." (PMID 35052853, 2022). "In this systematic review, we analyzed ten studies that included 1118 patients with the precise aim of summarizing the existing literature on the role of NRP-2 in the EMT of colorectal cancer." (PMID 35052853, 2022). "Neuropilin-2 (NRP-2) expression has been found in various investigations on the expression and function of NRP-2 in colorectal cancer." (PMID 35052853, 2022). "The link between NRP-2 and colorectal cancer, as well as the mechanism that regulates it, is still mostly unclear." (PMID 35052853, 2022). "Despite increasing evidence of the tumoral Nrp2 association with CRC progression, mechanisms underlying Nrp2-mediated colorectal cancer growth and metastasis remain elusive." (PMID 35158941, 2022). "The ten studies have found that NRP-2 is a promising therapeutic target since its expression is required for colorectal cancer cell proliferation and metastasis." (PMID 35052853, 2022). "The NRP-2 is a possible therapeutic target in human malignancies where it is expressed and is critical for tumor formation in colorectal carcinoma cells." (PMID 35052853, 2022). "Treatment of mice with NRP-2 siRNA inhibited the growth of colorectal cancer hepatic metastases, providing proof-of-principle for treatment with small RNA molecules against NRP-2." (PMID 24142150, 2014). "Altogether, these results identified a direct role for NRP2 on EMT promotion in colorectal cancer cells." (PMID 21747928, 2011). "Then, we assessed the influence of TGFRI pharmacological inhibition on vimentin and E-cadherin levels in NRP2 expressing colorectal cancer cell lines." (PMID 21747928, 2011). "Then, we sought to investigate the ability of neuropilin-2 to orchestrate epithelial-mesenchymal transition in colorectal cancer cells." (PMID 21747928, 2011). "A treatment with 50 μM of SB-431542 during 16 hours induced the relocalization of beta-catenin at the membrane of tumor cells, indicating that TGFRI activity neutralization can reverse EMT in NRP2 expressing colorectal cancer cells." (PMID 21747928, 2011). "Collectively, these results suggest that NRP2 cooperates with TGFβRI to promote EMT in colorectal carcinoma." (PMID 21747928, 2011).